NSUN2 (NOP2/Sun RNA methyltransferase 2)
Diseases named in the same sentence as NSUN2 in open-access papers (continued):
Sharing a sentence is not in itself a finding about the gene and the disease.
tumor (continued). "IHC of tumour tissues from the negative control group showed that the expression of NSUN2 was correlated with the expression of AR (r2 = 0.4667, p = .0050) and AR‐V7 (r2 = 0.2800, p = .0425)." (PMID 36169095, 2022). "The expression of ALKBH1 (p = 0.036), ALYREF (p < 0.001), NOP2 (p < 0.001), NSUN2 (p < 0.001), NSUN4 (p < 0.001), NSUN5 (p < 0.001), NSUN6 (p < 0.001), NSUN7 (p = 0.006), and YBX1(p < 0.001) were significantly upregulated in tumor tissues compared with the adjacent mucosa." (PMID 35281843, 2022). "In this study, we demonstrated that NSUN2 was highly expressed in NPC and might predict a poor prognosis because it was closely correlated with the tumor stage and distant metastasis in the GEO database and our own cohorts." (PMID 35574373, 2022). "NSUN2 modified 3'UTR of TEA domain transcription factor 1 (TEAD1) mRNA with m5C which promotes the expression of TEAD1, thereby enhancing the proliferation and invasion of tumor cells." (PMID 35562754, 2022). "Tumour volume and weight were markedly decreased in the shRNA‐treated group and increased in the NSUN2 OE group compared with the negative control group." (PMID 36169095, 2022). "NSUN2-induced m5C in CDK1 mRNA promotes CDK1 translation, leading to tumor cell proliferation." (PMID 33922187, 2021). "Although NSUN2 overexpression was reported to promote metastasis and cell invasion by promoter methylation 109, these studies explicitly indicate that NSUN family-induced RNA m5C modifications play a pivotal role in tumor metastasis and cell motility." (PMID 34512153, 2021). "NSUN2 has been identified as an MYC target correlated to the MYC-dependent proliferation in tumors, and DNMT2 is highly expressed in various tumor tissue cells, implying that DNMT2 functions an oncogenic role in tumorigenesis." (PMID 34272618, 2021). "Lack of Nsun2 in mice leads to an increase in undifferentiated tumor stem cells due to decreased global translation, which increases the self-renewal potential of the tumor-initiating cells." (PMID 29061143, 2017). "In vivo, NSUN2 depletion potentiated the antitumor activity of OXA in SW480 xenografts, and combining OXA with the ferroptosis inducer imidazole ketone erastin (IKE) further reduced tumor burden compared with OXA alone, accompanied by increased tumor MDA levels." (PMID 41808866, 2026). "The expression of NONO and NSUN2 was higher in the gastric tissue, which was in contrast to the expression of PTEN, suggesting that the NONO-NSUN2-PTEN regulatory axis is a bona fide signaling pathway critical to tumor pathogenesis and patient prognosis in human GC." (PMID 40033337, 2025). "In tumors with elevated NSUN2 expression, simultaneous NSUN2 inhibition and ICI therapy may achieve synergistic antitumor effects: NSUN2 inhibition attenuates tumor-derived immunosuppressive signaling, while ICIs restore T cell function, resulting in dual immune activation." (PMID 41256859, 2025). "However, there was no discernible correlation between NSUN2 expression and gender, age, or tumor-distant metastasis." (PMID 38403250, 2024). "Consequently, overexpression of wild type NSUN2, but not the catalytic mutant NSUN2, leads to gefitinib resistance and tumor recurrence, while depletion of NSUN2 results in tumor regression and overcomes intrinsic resistance to gefitinib." (PMID 37161388, 2023). "Notably, overexpression of NSUN2-WT but not NSUN2-DM significantly shortened survival of the tumor-bearing mice (p = 0.0233) and decreased efficacy of gefitinib treatment compared to Mock group." (PMID 37161388, 2023). "Since the NSUN2/ALYREF/m5C‐PFAS oncogenic cascade is an important trigger of RB, our study provides a novel targeted m5C reprogramming therapeutic strategy, which may potentially be an efficient anti‐tumour therapy approach." (PMID 37228185, 2023).
tumor (continued). "Since the NSUN2/ALYREF/m5C‐PFAS oncogenic cascade is an important trigger of RB, our study provides a novel therapeutic strategy, namely, a ‘targeted m5C reprogramming strategy’, that may potentially be an efficient anti‐tumour therapy." (PMID 37228185, 2023). "Moreover, five writers (NOP2, NSUN2, NSUN3, NSUN4 and NSUN5), one reader (ALYREF) and two erasers (TET2 and TET3) were consistently upregulated in UCB tumor tissues compared to adjacent normal tissues from TCGA cohort (fold change > 1.1, P-value <0.05, occurrence rate > 50%)." (PMID 36806253, 2023). "As the NSUN2/ALYREF/m5C‐PFAS oncogenic cascade is an important RB trigger, our study suggests that a targeted m5C reprogramming therapeutic strategy may be a novel and efficient anti‐tumour therapy approach." (PMID 37228185, 2023). "Furthermore, NSUN2 negatively regulates immune cell infiltration in the tumor microenvironment (TME) of NPC, which indicates that the NSUN2 level may be negatively correlated with the sensitivity of immunotherapy and chemotherapy." (PMID 35574373, 2022). "Considering the role of TME in tumor occurrence and development and its prognostic impact, we used three data sets (i.e., GSE114727-inDrop, BRCA_GSE110686, and BRCA_GSE114727_10X) in the TISCH database to analyze the expression of NSUN2 and NSUN6 in TME-related cells." (PMID 33928086, 2021). "However, NSUN2 was initially identified for its role in maintaining spindle stability during mitosis as part of an RNA–protein complex, which implies that some of the functions of NSUN2 in tumours may not depend on m5C modification." (PMID 40156167, 2025). "IHC analysis of 40 GC tumors illustrated an increased global RNA m5C content in tumor samples and the m5C methylation levels of tissue correlated positively with NONO and NSUN2 expression." (PMID 40033337, 2025). "In line with our in vitro observations, simvastatin exhibited no notable alteration in NSUN2 and HMGCR expression in PDX-1-derived tumor specimens." (PMID 40713894, 2025). "In addition, in skin cancer, a lack of NSUN2 specifically sensitizes tumour-initiating cells to 5-FU, further showing that the combination of classic chemotherapeutic agents and the inhibition of RNA modifications could become a more effective therapeutic strategy." (PMID 35205419, 2022). "We compared circNSUN2 and NSUN2 mRNA levels in a nontumorous tissue, three CRC tumor tissues, and five CRC cell lines by RT-PCR and real-time PCR (qRT-PCR)." (PMID 31619685, 2019).
cancer (108 papers, 2014 to 2026). A tumor composed of atypical neoplastic, often pleomorphic cells that invade other tissues. "In cancer, abnormal NSUN2 expression is associated with the occurrence and development of various cancers, such as oral cancer and rectal cancer." (PMID 41501031, 2026). "In vitro, NSUN2 deficiency significantly impaired the proliferation, survival, and invasiveness of cancer cells, effects that were fully reversed by exogenous glucose supplementation." (PMID 40765828, 2025). "The levels of NSUN2 expression in tumors have prognostic value in certain cancers, such as high NSUN2 portends poor outcome and greater metastatic risk." (PMID 41301491, 2025). "Higher NSUN2 expression is linked to more advanced cancer stages and heightened drug resistance, while elevated YBX1 expression correlates with poorer patient survival." (PMID 40114967, 2025). "Loss-of-function of NSUN2 in cancer cells leads to reduced methylation of many RNAs, often resulting in decreased stability of pro-migratory transcripts and a subsequent decline in invasion." (PMID 41301491, 2025). "In conclusion, NSUN2 rs13181449 was associated with lower cancer risk, especially for cigarette smokers." (PMID 40657390, 2025). "NSUN2 is dysregulated in various types of cancers through mutations or translational modifications such as lactylation." (PMID 40713894, 2025). "Research highlights NSUN2’s pivotal role in cancer progression, closely associated with poor prognosis." (PMID 40444266, 2025). "In tumors, aberrant NSUN2 expression is closely associated with the occurrence, progression, and prognosis of various cancers." (PMID 41256859, 2025). "As NSUN2 is the key enzyme mediating global m5C RNA methylation in various cancer cell lines 47, 48, we further found that both glucose deprivation and NSUN2 deficiency resulted in a marked decrease in global m5C RNA methylation levels." (PMID 40765828, 2025). "NSUN2, an m5C methyltransferase, has been implicated in various cancers, but its role in HNSCC remains elusive." (PMID 39595099, 2024). "Azetidine acrylamides, stereoselective covalent inhibitors of human NSUN2, can cause a global reduction in tRNA m5C content in cancer cells." (PMID 39006762, 2024). "To identify the target gene associated with NSUN2-regulated cancer progression, we conducted RNA-seq on NSUN2-overexpressing A549 cells." (PMID 38403250, 2024). "NSUN2 expression alterations have been linked to several cancer types including breast, skin, colon, ovarian, oesophageal, bladder, gallbladder, gastric cancer, and head and neck squamous carcinoma." (PMID 33461542, 2021). "Mutation or aberrant expression of NSUN2 is involved in various diseases, such as cancer and developmental disorders [12, 21−23]." (PMID 34345012, 2021). "Similar to NSUN2 deletion, dysregulation of the one-carbon metabolism impairs foetal growth and has been linked to neurodevelopmental disorders and cancer." (PMID 31199786, 2019). "NSUN2 is a RNA methyltransferase that has been shown to be implicated in development of human cancer." (PMID 27447970, 2017). "Our analysis identified three candidate genes with increased expression in cancer tissues, with elevated levels associated with poor survival across multiple cancer types: the 5-methylcytosine methyltransferases NSUN2 and DNMT3B and CBP20, an N7-methylguanosine binding protein." (PMID 40887503, 2025). "As such, specifically targeting lactylated NSUN2 by interfering its association with NAA10 may constitute a promising therapeutic approach in cancer treatment." (PMID 39742570, 2025). "NSUN2, a key m5C methyltransferase, has been implicated in various cancers, but its role in NPC remains unclear." (PMID 41463199, 2025). "Overall, NSUN2 was highly expressed and related to a poor prognosis in most types of cancers and was also significantly associated with immune molecular subtypes in some cancer types." (PMID 37769000, 2023).
cancer (continued). "Indeed, in Nsun2 deficient mouse cancer cells, ribosome profiling data showed an increased translation of genes associated to stress response pathways and decreased translation of genes associated to differentiation." (PMID 33461542, 2021). "Furthermore, m5C bisulfite sequencing (Bis-seq) in NSUN2-deficient GC cells showed that m5C-methylated genes are involved in multiple cancer-related signaling pathways." (PMID 34504059, 2021). "Nevertheless, the underlying mechanism of NSUN2 function in cancer requires further exploration." (PMID 34504059, 2021). "Although detailed mechanisms between NSUN2 mutation, cigarette smokers, and cancer development are unknown, it might be because cigarette smoking might increase HIF-1-alpha levels, which mediated RNA modification through complex regulation, such as cell cycle, PI3K-AKT pathway, and others 44-46." (PMID 40657390, 2025). "In addition, NSUN2 protein level was positively associated to the individual cancer stages." (PMID 35280737, 2022). "However, it is unclear whether the underlying molecular mechanisms of NSUN2 in other cancers can regulate mRNA modification." (PMID 36360287, 2022). "Therefore, the SUMOylation–NSUN2–m5C axis may represent a new diagnostic and therapeutic target for GC and pan-cancer treatment." (PMID 34504059, 2021). "Research has shown that the expression level of NSUN2 is elevated in various cancers and that its mediated tRNA m5C modification can significantly affect the efficiency and accuracy of protein translation." (PMID 41501031, 2026). "Overall, our present study demonstrated that NAA10-catalyzed lactylation of NSUN2 potently promotes cancer cell survival through a GCLC-dependent glutathione synthesis." (PMID 39742570, 2025). "This study is the first to focus on how NSUN2 changes the m5C methylation and leads to the development of cancer in OSCC." (PMID 41436732, 2025). "Through these sites, NSUN2 modulates gene m5C activity, playing a substantial role in cancer progression." (PMID 41413017, 2025). "NSUN2 is the most important RNA methyltransferase to induce m5C to specific RNAs that regulate the malignant behaviour of various cancers 57-60." (PMID 40860147, 2025). "Concurrently, the development of potent and specific NSUN2 inhibitors and preclinical validation of their safety and efficacy in combination with ICIs will provide novel strategies for precision cancer immunotherapy." (PMID 41256859, 2025). "The expression status of NSUN2 was examined via a TNM plot across a range of cancer types in The Cancer Genome Atlas (TCGA)." (PMID 41436732, 2025). "For instance, NSUN2-mediated RNA m5C modification promotes cell proliferation, migration, and invasion in various cancers such as breast cancer and gallbladder cancer and correlates with adverse outcomes in head and neck squamous cell carcinoma." (PMID 40444266, 2025). "The impact of NSUN2 rs4702373, rs166049, rs13181449, and rs8192120 on cancer development and prognosis were analyzed." (PMID 40657390, 2025). "A wealth of research indicates that NSUN2 was highly expressed in a variety of cancers and functions to regulate downstream mRNA expression, stability or translation in a m5C‐dependent manner, and ultimately promoting malignant progression." (PMID 40156167, 2025). "Overall, these findings imply that GCLC is an indispensable downstream effector of lactylated NSUN2 in modulating ferroptosis resistance to promote cancer cell survival." (PMID 39742570, 2025). "Collectively, these data highlight NSUN2 as a promising therapeutic target for combination cancer treatments involving chemotherapy or TKIs." (PMID 40083919, 2025). "NSUN2 is the most common m5C RNA methylase in BCa, which is also highly expressed in cancer cell, and its role in BCa cell has been revealed." (PMID 41354740, 2025). "Prognostic roles of NSUN2 were also presented in various cancers, including gastric cancer, breast cancer, and others 27-29." (PMID 40657390, 2025).
cancer (continued). "NSUN2 is one of the m5C methyltransferases that has attracted the most attention because of its carcinogenic potential in a variety of cancer types." (PMID 41436732, 2025). "This review summarizes current insights into the roles and mechanisms of NSUN2 in cancer progression and immune modulation, and discusses challenges and future opportunities for therapeutic exploration." (PMID 41256859, 2025). "The 5-methylcytosine (m5C) RNA methyltransferase NSUN2 is involved in cell proliferation and metastasis and is upregulated in a variety of cancers." (PMID 39924557, 2025). "These inhibitors were shown to block the catalytic activity at the C271 site in recombinant NSUN2 and disrupt the NSUN2-tRNA interaction in cancer cells, resulting in decreased tRNA m5C content and suppression of cancer progression." (PMID 41413017, 2025). "Azetidine acrylamides disrupt NSUN2-tRNA interactions in cancer cells, leading to a global reduction in tRNA m5C content, thus mediating mitochondrial functions." (PMID 41373022, 2025). "Recent reports have shown that ectopic expression of NSUN2 drives ferroptotic resistance in cancer cells through modulating a list of target genes, such as SLC7A11, NRF2 and GPX4." (PMID 39742570, 2025). "Our study demonstrates that GCLC mRNA, the catalyzing enzyme subunit of GSH synthesis, is the special target of lactylated NSUN2, through which cancer cells maintain a redox homeostasis under acidic TME." (PMID 39742570, 2025). "Detailed mechanisms were suggested to support our findings, especially for the relationship between NSUN2 rs13181449, cigarette smokers, and cancer development." (PMID 40657390, 2025). "In previous study, the role of RNA modification, such as RNA methylation mediated by the NSUN2 gene, was discussed, especially in cancer development and prognosis." (PMID 40657390, 2025). "NSUN2 also promotes the maturation of its upstream transcription factor c-Myc and exhibits broad anti-cancer effects in both in vitro and in vivo experiments." (PMID 40463874, 2025). "The positive feedback between NSUN2 and AR provides novel evidence that m5C modification clusters exist in PCa and explain cancer progression and the occurrence of castration-resistant PCa." (PMID 40860147, 2025). "Specifically, the effect of NSUN2 lactylation-GCLC-GSH pathway is nearly lost when NSUN2 K508R or GCLC C-A mutant (five cytosine sites) was introduced into the cancer cells." (PMID 39742570, 2025). "While NSUN2 has been reported to influence cancer development, chemoresistance, and oxidative stress, there has been limited research on its role in ferroptosis." (PMID 38403250, 2024). "Among these potential targets, two oncogenes, MYBL2 and RAD54L, which were previously demonstrated to be targets of E2F145–49, were downregulated in both cancer cell lines upon NSUN2 knockdown." (PMID 38424195, 2024). "NSUN2-mediated mRNA m5C modification has been reported to primarily influence mRNA stability or translation efficiency across various cancers." (PMID 38403250, 2024). "Our study uncovered a novel KEAP1-independent mechanism for NRF2 activation, suggesting the theoretical feasibility of developing a drug targeting NSUN2 to reduce the overall m5C level and malignant phenotype of cancer cells." (PMID 38403250, 2024). "For example, NSUN2-mediated m5C tRNA modification can promote drug resistance, differentiation, and self-renewal of cancer cells." (PMID 39019857, 2024). "Overall, these findings showcase NSUN2 as a promising target for cancer immunotherapy in combination with immune checkpoint blockade." (PMID 38769664, 2024). "The 5-methylcytosine RNA methyltransferase NSUN2, which is upregulated and involved in cell proliferation and metastasis in various cancers, can enhance the carcinogenic ability by being stabilized by sumoylation." (PMID 39742381, 2024). "To further investigate the impact of LAMC2 on NSUN2-induced cancer progression, we established SCC25 and HSC3 cell lines with LAMC2 knockdown." (PMID 39595099, 2024).